ST3GAL2 (ST3 beta-galactoside alpha-2,3-sialyltransferase 2)
Description:
A beta-galactoside alpha2-3 sialyltransferase primarily involved in terminal sialylation of ganglio and globo series glycolipids. Catalyzes the transfer of sialic acid (N-acetyl-neuraminic acid; Neu5Ac) from the nucleotide sugar donor CMP-Neu5Ac onto acceptor Galbeta-(1->3)-GalNAc-terminated glycoconjugates through an alpha2-3 linkage. Sialylates GM1/GM1a, GA1/asialo-GM1 and GD1b gangliosides to form GD1a, GM1b and GT1b, respectively. Together with ST3GAL3, primarily responsible for biosynthesis of brain GD1a and GT1b that function as ligands for myelin-associated glycoprotein MAG on axons, regulating MAG expression and axonal myelin stability and regeneration (By similarity). Via GT1b regulates TLR2 signaling in spinal cord microglia in response to nerve injury (By similarity). Responsible for the sialylation of the pluripotent stem cell- and cancer stem cell-associated antigen SSEA3, forming SSEA4. Sialylates with low efficiency asialofetuin, presumably onto O-glycosidically linked Galbeta-(1->3)-GalNAc-O-Ser.
Synonyms: ST3GalII; SIAT4B; ST3GalA.2; Gal-NAc6S
Tractability: Antibody: UniProt places it where antibodies can reach, with medium confidence; UniProt predicts a signal peptide or a membrane-spanning region; its Gene Ontology location is reachable by antibodies, with medium confidence. PROTAC: its protein half-life has been measured.
Gene: Protein-coding gene on chromosome 16 (70,375,977 to 70,439,263, reverse strand). Ensembl gene ENSG00000157350.
Subcellular location: Golgi apparatus, Golgi stack membrane; Secreted
Subcellular location (Human Protein Atlas): Vesicles
Pathways (Reactome):
Disease: Maturation of protein 3a; Maturation of spike protein
Metabolism: Glycosphingolipid biosynthesis; Keratan sulfate biosynthesis
Metabolism of proteins: Sialic acid metabolism; Termination of O-glycan biosynthesis
Gene Ontology:
Molecular function: beta-D-galactosyl-(1->3)-N-acetyl-beta-D-galactosaminide alpha-2,3- sialyltransferase; beta-galactoside (CMP) alpha-2,3-sialyltransferase activity; protein homodimerization activity; sialyltransferase activity
Biological process: ganglioside biosynthetic process; globoside biosynthetic process; glycolipid biosynthetic process; glycoprotein biosynthetic process; oligosaccharide biosynthetic process; sialylation; glycosphingolipid biosynthetic process; keratan sulfate proteoglycan biosynthetic process; protein O-linked glycosylation via N-acetyl-galactosamine; viral protein processing
Cellular component: Golgi membrane; membrane; extracellular region; Golgi cisterna membrane
Genetic constraint (gnomAD): Loss-of-function variants: 16 observed, 39.38 expected, observed/expected ratio (o/e) 0.41, 90% interval 0.27 to 0.62. The upper end of that interval is the gene's LOEUF score, 0.62, which puts it in group 2 of 6, group 1 being the genes least tolerant of losing a copy. Missense variants: 383 observed, 513.76 expected, observed/expected ratio (o/e) 0.75, 90% interval 0.69 to 0.81. Synonymous variants: 238 observed, 212.6 expected, observed/expected ratio (o/e) 1.12, 90% interval 1.01 to 1.25.
Homologues: Orthologues: chimpanzee ST3GAL2 (99% identical), macaque ST3GAL2 (99% identical), guinea pig ST3GAL2 (98% identical), pig ST3GAL2 (97% identical), mouse St3gal2 (94% identical), rat St3gal2 (94% identical), rabbit ST3GAL2 (86% identical), dog ST3GAL2 (77% identical), tropical clawed frog st3gal2 (76% identical), zebrafish st3gal2 (71% identical). Paralogues in human: ST3GAL1 (47% identical), ST3GAL3 (23% identical), ST6GALNAC1 (23% identical), ST6GALNAC2 (22% identical), ST3GAL4 (22% identical), ST3GAL5 (21% identical), ST6GAL2 (18% identical), ST6GALNAC4 (18% identical), ST6GAL1 (18% identical), ST3GAL6 (17% identical), ST6GALNAC5 (17% identical), ST6GALNAC6 (16% identical), and 2 more.
Diseases named in the same sentence as ST3GAL2 in open-access papers:
ST3GAL2 is named in the same sentence as 29 diseases in open-access papers, as found by Europe PMC text mining. Sharing a sentence is not in itself a finding about the gene and the disease. The quoted sentences say what the papers report.
breast carcinoma (3 papers, 2015 to 2021). "It has been found that ST3GAL2 is a poor prognostic factor in breast cancer patients treated with chemotherapy." (PMID 35071226, 2021). "Elevated expression of CMP-N-acetylneuraminate-β-galactosamide-α-2,3-sialyltransferase 2 (ST3GAL2), the enzyme catalyzing the last step of SSEA4 synthesis, is associated with poor prognosis in breast cancers treated with chemotherapy." (PMID 26607327, 2015). "SSEA4 and ST3GAL2 may therefore represent key markers to classify patient groups in order to avoid ineffective and painful therapies and to develop alternative treatment regimens for breast cancer patients." (PMID 26607327, 2015).
cognitive deficits (2 papers, 2020 to 2021). "For example, it was seen that mice deficient in sialyltransferases St3gal2 and St3gal3 (mainly involved in the assembly of gangliosides) presented motor impairments and cognitive deficits, besides increased dysmyelination, indicating the crucial role of sialylation." (PMID 33993882, 2021).
dilated cardiomyopathy (2 papers, 2019 to 2022). Cardiomyopathy which is characterized by dilation and contractile dysfunction of the left and right ventricles. "Similarly, sialyltransferases have been found altered in ischemic myocardium, and overexpression of ST3Gal2 is associated with dilated cardiomyopathy." (PMID 36361941, 2022). "For example, the glycomic profiles of FFPE heart sections of beta-galactoside alpha-2,3-sialyltransferase 2 (St3gal2)-transgenic mice as a model with dilated cardiomyopathy that were obtained in our recent study may be valuable data." (PMID 31443278, 2019).
oral squamous cell carcinoma (2 papers, 2021). "Furthermore, elevated ST3GAL2 and ST3GAL3 mRNA expression is associated with advanced stages of oral squamous cell carcinoma with lymph node involvement, suggesting a role of these two sialyltransferases in oral squamous cell carcinoma progression." (PMID 33921986, 2021).
ovarian carcinoma (2 papers, 2015 to 2017). A malignant neoplasm originating from the surface ovarian epithelium. "In light of these results, we evaluated whether ST3GAL2 expression could be associated with patient prognosis in ovarian cancer." (PMID 26607327, 2015). "Finally, high expression of CMP-N-acetylneuraminate-β-galactosamide-α-2,3-sialyltransferase 2 (ST3GAL2), the rate-limiting enzyme of SSEA4 synthesis, was found to be associated with poor clinical outcome in breast and ovarian cancer patients treated with chemotherapy." (PMID 26607327, 2015). "Furthermore, we have shown that the expression level of ST3GAL2, the enzyme catalyzing SSEA4 synthesis, can be used as a marker to predict clinical outcome of breast and ovarian cancer patients, in particular those treated with chemotherapy." (PMID 26607327, 2015).
Parkinson disease (2 papers, 2021 to 2023). A progressive degenerative disorder of the central nervous system characterized by loss of dopamine producing neurons in the substantia nigra and the presence of Lewy bodies in the substantia nigra and locus coeruleus. "It is known that in rats suffering from Parkinson’s disease there is also an increase in PV-positive interneurons in the M1 region, which may be related to the impaired motor activity of St3gal2/3-double null mice." (PMID 38139047, 2023).
viral infection (2 papers, 2017 to 2025). "ST3GAL2 resists viral infection by downregulating pro-inflammatory cytokines (IL-6, IL-18, IL-1β, IFN-β, TNF-α) and upregulating anti-inflammatory cytokines (IL-4, IL-10, IL-13)." (PMID 40755778, 2025).
breast tumors (1 paper, 2015). "Given the functional connection between SSEA4 and ST3GAL2, we evaluated the clinical value of ST3GAL2 in a large, publicly available clinical microarray database of breast tumors from 2977 patients." (PMID 26607327, 2015).
diabetes (1 paper, 2023). "Of the 15 top candidate genes, ST3GAL2, AASS, ARF1 and the transcription factor SIN3A are novel candidates for predicting a refined diabetes risk and intervention response." (PMID 36790478, 2023).
glioma (1 paper, 2023). A benign or malignant brain and spinal cord tumor that arises from glial cells (astrocytes, oligodendrocytes, ependymal cells). "Analysis of the primary glioma data showed that members of the ST3GAL family, specifically ST3GAL2 and ST3GAL4, exhibited higher levels of expression." (PMID 38067186, 2023).
hepatocellular carcinoma (1 paper, 2017). A malignant tumor that arises from hepatocytes. "In this study, we examined the expression of their biosynthetic enzymes, FUT1, FUT2, B3GALT5 and ST3GAL2, in 135 hepatocellular carcinoma (HCC) tissues by qRT-PCR." (PMID 28883415, 2017).
Insulin resistance (1 paper, 2025). Increased resistance towards insulin, that is, diminished effectiveness of insulin in reducing blood glucose levels. "The ST3GAL2 deficiency disrupted insulin signaling by impairing insulin receptor-mediated phosphorylation in adipose tissue but not liver or skeletal muscle, leading to hyperglycemia and insulin resistance." (PMID 41301440, 2025). "Mice lacking ST3GAL2, characterized by altered ganglioside composition in adipose tissue, developed late-onset obesity and insulin resistance on a standard diet." (PMID 41301440, 2025).
Obesity (1 paper, 2021). Accumulation of substantial excess body fat. "In particular, three obesity-related BSAGs (ST3GAL2, ZGRF1 and ZPLD1) were determined to have undergone rapid evolution in extremely large carnivores, although this was not significant in any of the three after FDR correction." (PMID 34107880, 2021).
pharyngeal cancer (1 paper, 2022). "MR analysis showed that ST3GAL2, which is elevated in noisy workplaces, is a risk factor for oropharyngeal, oral cavity, and pharyngeal cancer." (PMID 35602164, 2022).
triple-negative breast carcinoma (1 paper, 2022). An invasive breast carcinoma which is negative for expression of estrogen receptor (ER), progesterone receptor (PR), and human epidermal growth factor receptor 2 (HER2). "In addition to ST3GAL1, the elevated levels of ST3GAL2 and its product sialyl-glycolipid stage-specific embryonic antigen 4 (SSEA4) were suggested for the increased chemoresistance of triple-negative breast cancer to genotoxic agents." (PMID 36092699, 2022).
tumor (11 papers, 2010 to 2025). "RT-qPCR of both in vitro and in vivo tumor cells also revealed significant up-regulation of key enzymes involved in glycosphingolipid biosynthesis, including St3gal1, St3gal2, B4galt5, Sptlc2, and Ugcg, in A159V-mutated cells." (PMID 41160695, 2025). "The ST3GAL2 showed a significant association with number of tumor nodules (P = 0.003), Edmonson-Steiner grade (P = 0.008) and relapse (P = 0.042)." (PMID 28883415, 2017). "When compared to low expression of ST3GAL2, patients with high expression of ST3GAL2 were at higher risk for multiple tumors (OR: 3.22, 95% CI: 1.46–7.13), moderately and poorly differentiated tumor (OR: 2.66, 95% CI: 1.28–5.53) and relapse (OR: 2.13, 95% CI: 1.02–4.45)." (PMID 28883415, 2017). "Thus, we propose SSEA4 as a novel marker for EMT-associated chemotherapy resistance and ST3GAL2 expression as a predictive marker for tumor resistance to chemotherapy." (PMID 26607327, 2015). "We examined the mRNA expression levels of the FUT1, FUT2, B3GALT5 and ST3GAL2 in tumor specimens of 135 HCC patients by qRT-PCR." (PMID 28883415, 2017). "Through in silico analysis we showed that mRNAs of only ST6GAL1, ST3GAL2 and ST8SIA4 are significantly upregulated in GBM tissues compared to non-tumor ones." (PMID 41226744, 2025). "Meanwhile, the GEPIA database showed that JUP, ITGB4, ST3GAL2, ST3GAL5 and B4GALNT1 were higher expressed in tumor samples than in paired normal tissues." (PMID 34402716, 2021). "To provide further evidence of the relationship between ST3GAL2 and SSEA4, we compared ST3GAL2 mRNA levels with SSEA4 cell surface levels on nine different tumor models, which showed significant positive correlation (p < 0.002)." (PMID 26607327, 2015). "The molecular mechanisms by which ST3GAL2 directly or indirectly contributes to tumor progression are not clear." (PMID 28883415, 2017). "Tumor cells highly expressed donor synthesis genes (NANS, CMAS, and the transporter SLC35A1), while the stroma showed enriched expression of sialyltransferases involved in α2-3, α2-6 and α2-8 sialylation (ST3GAL2, ST3GAL5, ST6GAL2, ST6GALNAC5, ST6GALNAC6, ST8SIA1 and ST8SIA2)." (PMID 38594506, 2024).
cancer (6 papers, 2015 to 2025). A tumor composed of atypical neoplastic, often pleomorphic cells that invade other tissues. "α2,3-Sialyltransferases ST3GAL2 and ST3GAL3 are responsible for sialyl-Lewis(x) synthesis, which is associated with cancer aggressiveness." (PMID 35071226, 2021). "Intriguingly, Kaplan Meier analysis revealed poorer survival for patients with higher levels of either ST6GAL1, ST3GAL2 and ST8SIA4, similarly to what observed in other cancer models." (PMID 41226744, 2025). "Recently, an alternative approach was followed in which the glycosyltransferases ST3GAL2, ST3GAL3, B4GALT5, and B3GALT4 were suggested as a further predictor in identifying GD2-positive phenotypes in cancer patients." (PMID 36551537, 2022). "In the CCLE database, expression of JUP, ITGB4, ST8SIA5, ST8SIA1, ST3GAL2, ST3GAL5 and B4GALNT1 in pan-cancer were explored." (PMID 34402716, 2021). "Combination with ten cancer types in pan-cancer, four mRNAs (PBX3, KLF6, ARHGAP1, ST3GAL2) were selected out." (PMID 32519740, 2020).
infection (4 papers, 2021 to 2025). The state of being infected such as from the introduction of a foreign agent such as serum, vaccine, antigenic substance or organism. "However, only the infection with G9P was associated with a significant downregulation of the expression of genes encoding ST3Gal (ST3Gal2, ST3Gal3, and ST3Gal6) and ST6Gal (ST6Gal1) sialyltransferases." (PMID 37515094, 2023). "Nevertheless, the majority of our results reveal that the expression of the sialyltransferase ST3GAL2 is regulated during infection with C. jejuni 81-176 by miR-615-3p." (PMID 34183045, 2021). "Herein, ST3GAL2 has been identified as a target of miR-615-3p in vitro and for the first time we show a regulatory relationship of miR-615-3p and ST3GAL2 involved in the host cellular response to C. jejuni 81-176 infection in mice." (PMID 34183045, 2021). "Detection of ST3GAL2 in murine colonic tissue by immunofluorescence demonstrated reduced intensity after C. jejuni 81-176 infection and was thus consistent with the observations made above." (PMID 34183045, 2021). "Enhanced HU02Av−H5 infection of HEKΔSiaN cells upon transfection by ST3Gal1 (15% of WT) or ST3Gal2 (30% of WT) was unexpectedly observed which suggests that ST3Gal1 and 2 may indeed use type II LN substrates on N-glycans." (PMID 40487452, 2025). "Therefore, we examined their transcription in identical samples and observed a strongly reduced transcription (0.32-fold changes, P ≤ 0.0001) of ST3GAL2 elicited by C. jejuni 81–176 infection, which was anti-correlated with the miR-615-3p expression." (PMID 34183045, 2021). "The results of the in vivo experiments suggested that the mRNA level of ST3GAL2 might be modulated by miR-615-3p and miR-125a-5p may play a regulatory role on ST3GAL1 transcription in colonic tissue after C. jejuni 81–176 infection." (PMID 34183045, 2021).
bacterial infections (1 paper, 2021). "Moreover, we will shed light on the functional effects of miR-615-3p-ST3GAL2-interaction in response to other bacterial infections in future." (PMID 34183045, 2021).
neurodegenerative disease (1 paper, 2022). A disorder of the central nervous system characterized by gradual and progressive loss of neural tissue and neurologic function. "Therefore, our results suggest a downregulation of the glycan structures, derived from B3GALT4, ST3GAL2 and/or SLC35A1 genes, with ageing, a feature so far only described in neurodegenerative diseases." (PMID 36009354, 2022).
ST3GAL2 also shares sentences with these, for which no sentence is quoted: renal cell carcinoma (2 papers); Alzheimer disease (1); amyotrophic lateral sclerosis (1); colorectal cancer (1); Huntington disease (1); liver cirrhosis (1); melanoma (1); osteosarcoma (1); schizophrenia (1).